MTOR (mechanistic target of rapamycin kinase)
Diseases named in the same sentence as MTOR in open-access papers (continued):
Sharing a sentence is not in itself a finding about the gene and the disease.
glioma (continued). "The findings indicate ivermectin could induce autophagy-mediated cell death in glioma cells by inactivating AKT/mTOR signaling." (PMID 37998723, 2023). "However, Rictor, a component of the mTOR complex, induces glioma cell migration, increasing MMP-9 expression through the Raf-1-MEK-ERK signaling pathway." (PMID 36980765, 2023). "In addition, the results of flow cytometry and western bolt experiments confirmed that compound 1 induces glioma cell apoptosis by regulating the EGFR/PI3K/Akt/mTOR pathway." (PMID 37108310, 2023). "Thereof, designing targeted therapies that can enhance the levels of ROS and impede glioma proliferation via inhibition of PI3K/AKT/mTOR pathway are vitally important as they might improve glioma patient therapeutic outcome." (PMID 37025487, 2023). "D2-HG, a crucial metabolite produced by gliomas with IDH1 mutation, could potentially facilitate neuronal fusion by modifying neuronal molecular activity and triggering the mTOR signalling pathway." (PMID 38067243, 2023). "In addition, PrPC has been shown to protect glioma cells from autophagic cell death by targeting mammalian target of rapamycin (mTOR) activity." (PMID 37452879, 2023). "To study the role of mTORC1/2 regulation by FilGAP in glioma, we examined whether inhibition of mTOR or depletion of FilGAP affect tumorigenesis using 3D spheroid model of KINGS-1 and U-87MG cells." (PMID 38065968, 2023). "Further potential molecular based treatment options that have been investigated in IDH mutant glioma include the PI3K/mTOR signaling pathway that could be targeted with mTOR inhibition." (PMID 36566461, 2023). "Both the PI3K/Akt/mTOR and Ras/BRAF/Mek/Erk protein kinase pathways are also downstream of receptors such as EGFR, one of the most significant signaling pathways clinically implicated in glioma." (PMID 37445633, 2023). "Our bioinformatic analysis implied that the Hippo signaling pathway, MTOR pathway, WNT pathway et.al might be implicated in glioma malignant progression regulated by S100A16." (PMID 37151881, 2023). "mTOR regulates glioma survival, proliferation, and invasion." (PMID 38065968, 2023). "Molecular alterations in the PI3K/Akt/mTOR signaling pathway are typical of gliomas." (PMID 37592783, 2023). "The results suggest hirudin induces an autophagy in glioma cells through mTOR inactivation." (PMID 37539490, 2023). "In addition, amplification of the gene encoding the epithelial growth factor receptor (EGFR), a potent activator of the PI3K-Akt-mTOR pathway, observed in approximately 50% of GBMs, further underscores the importance of this pathway in glioma pathogenesis." (PMID 38275370, 2023). "A third group reported that the pro-seizure effects of IDHmut gliomas may be due to D2HG activation of neuronal mTOR." (PMID 37104042, 2023). "Furthermore, it promotes cancer cell metastasis via miR-451 and suppresses glioma cell proliferation and invasion in vitro and in vivo via suppression of the mTOR/HIF−1α/VEGF signaling pathway by targeting CAB39." (PMID 37511481, 2023). "The underlying mechanism was explored by network pharmacology and western bolt experiments, which indicated that compound 1 could induce glioma cells LN229 apoptosis by regulating the EGFR/PI3K/Akt/mTOR pathway." (PMID 37108310, 2023). "In addition, suppression of FAM83D has been shown to inhibit glioma cell proliferation, invasion, and migration by regulating the Akt- mammalian target of rapamycin (Akt-mTOR) signaling pathway." (PMID 36568373, 2022). "Interestingly, our results show that curzerene induces decreased phosphorylation of mTOR in gliomas and inhibits its downstream signal transduction." (PMID 35048517, 2022). "Here, we asked whether the activation of autophagy represents an escape mechanism to pharmacological mTOR inhibition in glioma cells, and explored co-treatment with mTOR and autophagy inhibitors as a therapeutic strategy." (PMID 36202792, 2022).
glioma (continued). "HSP60 activity has been previously demonstrated in glioblastoma, and the results reveal that HSP60 silencing inhibits glioma progression via deactivation of the mTOR pathway, suggesting that HSP60 is a possible therapeutic target for the treatment of glioblastoma." (PMID 36290736, 2022). "We hypothesized that mTOR inhibitors may protect glioma cells from hypoxia- and starvation-induced cell death through activation of autophagy." (PMID 36202792, 2022). "GAS5 may blunt the resistance of glioma cells to cisplatin by suppressing excessive autophagy through the activation of mTOR signaling, implying a promising therapeutic strategy against chemoresistance in glioma." (PMID 36245971, 2022). "In addition, it has been reported that activating or inhibiting autophagy by inhibiting or activating the mTOR pathway can inhibit the growth of gliomas by breaking the balance of autophagy." (PMID 35281871, 2022). "However, the renal cell carcinoma pathway, mTOR signalling pathway, glioma pathway, pancreatic cancer pathway and endocytosis pathway were the top signalling pathways affected by these differentially expressed microRNAs." (PMID 34986816, 2022). "Additionally, recent studies have shown that RES can promote caspase-3 activation in glioma cells by inhibiting the intracellular signaling pathway PI3K/Akt/mTOR." (PMID 35328780, 2022). "Similarly, GOLM1 promotes PDGFA/PDGFRα-mediated migration and invasion of glioma through the activation of PI3K/AKT/mTOR cascade, which, in turn, induces the activation of GSK3β and the increased expression of ZEB1 and Snail." (PMID 35805075, 2022). "Additionally, it has been observed to promote glioma growth and invasion via mTOR signalling and to promote malignant progression by attenuating the miR-384/PIWIL4/STAT3 axis, in accordance with our results." (PMID 35311131, 2022). "Similarly NVP-BEZ235—another a novel PI3K/mTOR inhibitor—had exhibited promising autophagy induction and enhanced radiosensitivity and apoptosis in human glioma stem cells through blocking the DNA damage repairing pathway." (PMID 36172166, 2022). "We found that silencing PTGFRN reduced ERK, AKT, and mTOR signaling in glioma cell lines." (PMID 35690717, 2022). "Hence, we investigated the effects of combined mTOR and autophagy inhibition on survival of glioma cells in the context of hypoxia and nutrient starvation." (PMID 36202792, 2022). "2-hydroxyglutarate (2HG) produced by IDH1/2 mutation promotes mTOR activity by depleting KDM4A and decreasing DEPTOR protein stability, presenting another mechanism of IDH1/2 mutation promoting the genesis of glioma and the possibility of a combination IDH inhibitor and mTOR inhibitor." (PMID 35785151, 2022). "Among these genes, DDIT4 activates the mTOR signaling pathway to promete the glioma progression." (PMID 35913967, 2022). "In the tumor microenvironment, ZFP36 might reduce the growth and invasion of glioma cells by targeting IL-13 mRNA to inhibit the role of PI3K/Akt/mTOR pathways." (PMID 35800363, 2022). "CBX3 has also been shown to regulate the c-Met/AKT/mTOR signaling pathway in glioma." (PMID 34785774, 2022). "Moreover, the involvement of this pathway in glioma cells was analyzed by applying PI3K/Akt/mTOR pathway inhibitor LY294002." (PMID 35494053, 2022). "The RTK/PI3K/Akt/mTOR cascade has long been known to boost glioma invasiveness." (PMID 35163279, 2022). "In addition, there are new drugs targeting epidermal growth factor receptor (EGFR) and mammalian target of rapamycin (mTOR) for the treatment of gliomas." (PMID 36605558, 2022). "AKT1, MTOR, CCND1, and EGFR are closely associated with autophagy and apoptosis in glioma." (PMID 35140796, 2022). "Moreover, the PI3K/Akt/mTOR signaling pathway has long been recognized to increase glioma invasiveness, angiogenesis, and migration." (PMID 36601479, 2022).
glioma (continued). "AKT plays an important role as a serine-threonine protein kinase in human malignancies, causing many downstream effects of PI3K, phosphorylating multiple substrates involved in regulating tumorigenesis, and promoting glioma cell survival through activation of mTOR, TSC2, and S6." (PMID 36479040, 2022). "Lastly, targeting mTOR is the most studied approach for the treatment of glioma." (PMID 35785151, 2022). "Then, we determined the effect of CAMK1D overexpression on PI3K/AKT/mTOR pathway in glioma cells." (PMID 35494053, 2022). "LINC0066312 may play a cancer-promoting role by accelerating the development and progression of glioma through the regulation of the Akt/mTOR pathway." (PMID 35647035, 2022). "As consequence of the deregulation of the PI3K/AKT/mTOR signaling in gliomas, the eIF signaling cascade might also play an important role during gliomagenesis." (PMID 33807050, 2021). "Overexpression of CRNDE promotes the growth and invasion of glioma cells through mTOR signaling." (PMID 34454479, 2021). "Moreover, the level of phosphorylated mTOR in the glioma cells was notably reduced at higher concentration of fucoxanthin." (PMID 34440090, 2021). "Collectively, these results revealed that RAP1B and CCND1 could activate the PI3K/AKT/mTOR signaling pathway in glioma cells." (PMID 33676540, 2021). "The PI3K/Akt/mTOR signaling pathway was explicit to participate in the regulation of cell proliferation, migration, invasion, mitochondrial dysfunction, induction of autophagy in glioma and anticancer therapy related to autophagy in cancers." (PMID 34454479, 2021). "Our result showed that PRELID1P6 promotes glioma progression through the hnHNPH1-Akt/mTOR pathway." (PMID 34108621, 2021). "The secreted ectodomain of Nlgn3 can act on glioma cells via unknown binding partners and recruits the phosphoinositide 3-kinase (PI3K)-mTOR pathway to promote glioma cell proliferation." (PMID 34690695, 2021). "The pathways included MAPK, ErbB, HIF-1B, mTOR, Pathways in cancer, Glioma, FoxO, Chronic myeloid leukemia, Renal cell carcinoma, Hepatitis B, Colorectal cancer, Protein processing in the endoplasmic reticulum, Fatty acid metabolism, ECM-receptor interaction, and Fatty acid biosynthesis." (PMID 33692799, 2021). "Upregulation of CASC2 through autophagy inhibition by buffering miR-193a-5p and regulating mTOR expression could sensitize glioma to TMZ cytotoxicity." (PMID 34178658, 2021). "In addition, endogenous mTOR co-immunoprecipitated with RIOK2 and BYSL in BYSL-overexpressing cells and endogenous BYSL co-immunoprecipitated with RIOK2 and mTOR in U251 glioma cells." (PMID 33628587, 2021). "However, other studies report that IMI inhibited signaling through PI3K/Akt/mTOR in U-87MG human glioma cells." (PMID 34832986, 2021). "GAS5 by suppressing excessive autophagy in an mTOR‐dependent manner could facilitate glioma cell sensitivity to cisplatin." (PMID 34178658, 2021). "In addition, circ-0037251 affects glioma cell proliferation and metastasis by regulating the miR-1229-3p/mTOR axis." (PMID 33413401, 2021). "In this study, we demonstrated that LINC00470 secreted by serum exosomes from glioma patients can bind miR-580-3p to regulate WEE1 expression and activate PI3K/AKT/mTOR signaling pathway, thus inhibiting glioma cell autophagy and promoting glioma cell proliferation." (PMID 33663509, 2021). "Additionally, the PI3K/Akt/mTOR signaling pathway is directly involved in the regulation of glioma cell proliferation, apoptosis, and metastasis." (PMID 34530814, 2021). "Therefore, we believe that TSN exerts anti-glioma effects through the PI3K/Akt/mTOR signaling pathway." (PMID 34530814, 2021). "But how PI3K/AKT/mTOR signaling pathway was activated and whether LINC00470 can regulate PI3K/AKT/mTOR signaling pathway in glioma are potential uncertainties for a better understanding of glioma." (PMID 33663509, 2021).
glioma (continued). "To sum up, we unearthed that M2 macrophage-derived miR-15a and miR-92a could target CCND1 and RAP1B, respectively, thereby inhibiting the invasion and migration via blocking PI3k/AKT/mTOR signaling pathway in gliomas." (PMID 33676540, 2021). "Since RTK/PI3K/mTOR is one of the most pivotal pathways regulating cell growth and survival in cancer biology, its targeting still remains a strong rationale for developing strategies against gliomas." (PMID 34063168, 2021). "In addition, NOTCH signaling activity has been reported in WHO grade IV gliomas, and can be associated with hypoxia, PI3K/AKT/mTOR and ERK/MAPK molecular pathways, increase malignant features of gliomas." (PMID 33790740, 2021). "The results demonstrated that LINC00470 in serum exosomes from glioma patients, through competing with WEE1 to bind miR-580-3p, could augment proliferation and impair the autophagy of glioma cells via activating PI3K/AKT/mTOR signaling pathway." (PMID 33663509, 2021). "Moreover, the combination of p-mTOR and YAP expression was negatively related to the overall survival of patients and associated with a high grade of glioma." (PMID 33477668, 2021). "Furthermore, the anti-glioma effect of TSN was exerted through the inhibition of the PI3K/Akt/mTOR signaling pathways as demonstrated by western blotting analysis." (PMID 34530814, 2021). "Moreover, downregulation of the PI3K/AKT/mTOR signaling pathway can reduce the migration and invasion of A172 glioma cells." (PMID 34204169, 2021). "Furthermore, the phosphorylation levels of Akt/mTOR signaling pathway proteins were decreased after PRELID1P6 knockdown in glioma cells." (PMID 34108621, 2021). "In addition, guanine supplementation partially rescued IDHmut glioma cell growth, mTOR signaling, and Cyclin D1 protein expression in vitro." (PMID 33681764, 2021). "In particular, the inhibition of PI3K’s downstream effectors, AKT and mTOR, may prove to reliably mitigate proliferation, motility and viability in glioma cells." (PMID 33472174, 2021). "In addition, Notch signaling activity is reported in WHO grade IV gliomas, and can be associated with hypoxia, PI3K/AKT/mTOR and ERK/MAPK molecular pathway and finally increase malignant features of gliomas." (PMID 34948224, 2021). "In addition, BCA treatment significantly inhibits the Warburg effect in U251 human glioma cells by regulating HIF-1a expression through the inactivation of the AKT/mTOR pathway." (PMID 34307130, 2021). "Furthermore, circPCMTD1 and hsa_circ_0037251 promote glioma cell proliferation and metastasis by regulating the mammalian target of rapamycin (mTOR) pathway via sponging of miR-224-5p and miR-1229-3p, respectively." (PMID 34745938, 2021). "Similarly, dual inhibition of PI3K and mTOR by one or more PKIs have demonstrated to be more effective in glioma treatment than inhibition of either target alone." (PMID 34884535, 2021). "In addition, overexpressing circPCMTD1 downregulates miR-224-5p and upregulates mTOR, thus aggravating glioma." (PMID 33413401, 2021). "Finally, a recent study showed that the phosphatidyl-inositol 3′ kinase (PI3K)/Akt/mammalian target of rapamycin (mTOR) pathway is involved in inducing VM in gliomas." (PMID 33036204, 2020). "Moreover, CDX-LIPO promoted M1-macrophage polarization and facilitated mTOR-mediated reprogramming of glucose metabolism in glioma." (PMID 32817393, 2020). "The role of mTOR in children and adult glioma was widely investigated." (PMID 32256210, 2020). "mTOR inhibitor omipalisib, which potently suppresses both mTORC1 and two activities, showed suppression of cell proliferation in both IDH1 wild type and mutated cells, which indicated that mTOR signaling plays essential roles in both glioma molecular subtypes." (PMID 32224866, 2020). "Additionally, metformin has been reported to increase the expression of AMPK while inhibiting the expression of mTOR, leading to cell death in glioma models." (PMID 32707662, 2020).
glioma (continued). "Furthermore, we demonstrated that celastrol reduced HIF-1α expression, and the phosphorylation of PI3K, Akt, and mTOR in U87 orthotopic glioma xenografts." (PMID 32116702, 2020). "However, the wnt pathway can form apparent crosstalk with PI3K/AKT/mTOR pathway to enhance glioma tumorigenicity." (PMID 33087705, 2020). "Thus, we supposed that PODNL1 aggravated malignant behaviors through Akt/mTOR pathway in glioma cells." (PMID 33033506, 2020). "Furthermore, circ-0014359 and circNT5E promoted glioma progression via PI3K/AKT/mTOR signaling pathway by miR-153 and miR422a, respectively." (PMID 32061256, 2020). "However, the limited single-agent activity of rapamycin analogs in several glioma trials provides a rationale for further testing other Akt-mTOR inhibitors against human glioma." (PMID 33159013, 2020). "The activation of the Akt-mTOR pathway was also validated in human glioma tissues." (PMID 32256210, 2020). "In addition, the activation of the mTOR signaling pathway correlates with an inhibition of the autophagic process, favoring the proliferation and pluripotency of glioma stem cells." (PMID 32707662, 2020). "Finally, we identify that AEBP1 exerts its tumor-promoting effects by mainly activating mTOR pathway in Glioma." (PMID 32938364, 2020). "In this study, we hypothesized that the exosomes, exosomal miRNAs, and the mTOR signaling pathway might be involved in hypoxic peritumoral neuronal injury in glioma." (PMID 33110474, 2020). "Therefore, we conclude that miR-450a-5p synergizes with gefitinib to inhibit the glioma tumorigenesis through inducing autophagy by regulating the EGFR-induced PI3K/AKT/mTOR signaling pathway, thereby enhancing the drug sensitivity of gefitinib." (PMID 32820249, 2020). "JMJD2A promotes glioma cell growth by activating the Akt-mTOR pathway." (PMID 32256210, 2020). "Moreover, PODNL1 promoted aggressive glioma behavior by activating Akt/mTOR pathway, providing a novel therapeutic target for glioma." (PMID 33033506, 2020). "In this study, our results demonstrated, for the first time, that celastrol might inhibit VM formation and angiogenesis in glioma orthotopic xenografts and glioma cells by regulating the PI3K/Akt/mTOR signaling pathway." (PMID 32116702, 2020). "To sum up, we found that miR-450a-5p can cooperate with gefitinib to inhibit the glioma tumorigenesis through inducing autophagy by regulating EGFR-induced PI3K/AKT/mTOR signaling pathway in glioma cells, thereby enhancing the drug sensitivity of glioma cells to gefitinib." (PMID 32820249, 2020). "Knockdown of CBX3 could reverse the inhibitory phenotypes or phosphorylation levels of Akt, mTOR and p70S6K caused by LINC00998 overexpression, which implied that CBX3 might be an essential protein for LINC00998 function in glioma." (PMID 33268783, 2020). "Therefore, XL388 induces significant cytotoxicity in glioma cells through Akt-mTOR-dependent and -independent mechanisms." (PMID 33159013, 2020). "Additionally, we provided evidence that the effects of JMJD2A on protein synthesis, cell proliferation, and colony formation were blocked by rapamycin, implicating that mTOR is essential for JMJD2A function in human glioma cells." (PMID 32256210, 2020). "Moreover, blocking of mTOR activity reinforced the sensitivity to EGFR-TKIs in glioma cells, while mTOR is also a downstream signaling molecule of PI3K-PTEN-Akt pathway." (PMID 32256584, 2020). "Overexpression of Gαi protein and RTK in gliomas formed the complex, and transducted Akt-mTOR signaling, which may be one of the reasons for promoting the growth of glioma U8MG cells." (PMID 32461938, 2020). "Our group has shown that overactivation of mTOR signaling is important for glioma cell progression." (PMID 33159013, 2020). "Several mTOR small molecule inhibitors are currently in clinical trials and may have some activity against human glioma." (PMID 33159013, 2020).